CCL5 (C-C motif chemokine ligand 5)
Diseases named in the same sentence as CCL5 in open-access papers (continued):
Sharing a sentence is not in itself a finding about the gene and the disease.
tumor (continued). "While the role of the CCL5/CCR5 axis in cancer has been a subject of conflicting reports, we found that CRCLM outgrowth increased in OVX mice treated with the CCR5 antagonist Mvc, suggesting a tumor-inhibitory role for CCL5 in this TME." (PMID 39007345, 2024). "Cytokines, including CCL2, CCL5, CCL18, TGFB1, and GDF15, are produced by tumor cells and attract immune cells, such as macrophages and lymphocytes, from the blood and bone marrow into the tumor microenvironment." (PMID 39272860, 2024). "The use of the inhibitors SB02024 or SAR405 to inhibit VPS34 kinase activity led to increased levels of CCL5, CXCL10, and IFN-γ in the tumor microenvironment (TME), resulting in increased levels of tumor infiltration by NK cells and T cells in melanoma and colorectal cancer models." (PMID 39124918, 2024). "Indeed, the expression of CCL5, IFNG, CXCL9 and CXCL10 positively correlated among themselves as well as with the numbers of tumor-infiltrating NK cells in the original biopsy." (PMID 38167224, 2024). "In the tumour microenvironment, CCL5 plays a crucial role in recruiting dendritic cells that predominantly present antigens to CD8+ T cells, and CXCL10 enhances the infiltration of CD8+ T cells into tumours." (PMID 38796460, 2024). "CCL5, a ligand of CCR5, is a product of cancer itself and its microenvironment, using the mTOR pathway through the regulation of cyclin D1, c-Myc, and Dad-1 expression to enhance tumor growth." (PMID 39329983, 2024). "In addition, tumor cell-derived conditioned medium (CM) containing abundant extracellular vesicles also increased α-SMA, FAP, IL-1, IL-6, IL-8, CCL5 and CXCL12 expression and enhanced the proliferation, motility and invasion of ADSCs." (PMID 38233863, 2024). "Comparative spatial analysis suggested that upregulation of ITGAM, CCL5 and CD27 and downregulation of BCL2 and HLA-E might be involved in the homing of macrophage within the tumor." (PMID 38064127, 2024). "These three signatures consist of myeloid-focused cytokines (TNFa, GM-CSF, and IL-1b), chemokines (CCL3, CCL4, CCL5, CXCL9, and CXCL10), and an effector T-cell-derived cytokine (IFNg) and represent important aspects of a macrophage-based anti-tumor immune response." (PMID 39199551, 2024). "Interestingly, an elevated level of the chemokine, C-C motif ligand 5 (CCL5), a chemoattractant, was also observed in the TME, which suggests that the T-cells were attracted to the tumour site." (PMID 39416707, 2024). "The generation, migration, proliferation, and maintenance of suppressive properties of MDSCs have also been reported to be induced by tumor-derived and hematopoietic CCR5 ligands like CCL3, CCL4, and CCL5 which can be produced by neutrophils, monocytes, NK cells, T cells, B cells and tumors." (PMID 38360737, 2024). "At the same time, the 1st released core was internalized by tumor cells and degraded by intracellular GSH, to realize a 2nd release of CDK4/6i in tumor cells, which induced an up‐regulated expression of CXCL10 and CCL5, and thus a significantly increased tumor infiltration of T cells." (PMID 38634209, 2024). "The application of a single cutoff for the staining status of tumor cells (TCs; positive vs. negative) and immune cells (ICs; positive vs. negative) revealed 75 patients (42.9%) and 123 patients (70.3%) with CCL5-positive TCs or ICs, respectively." (PMID 38928033, 2024). "CSC actively recruit Treg cells to the tumour microenvironment through the secretion of chemokines, such as CCL1, CCL2, and CCL5, a process that has been validated in a mouse glioblastoma model, in which CCL2 relies on the expression of CCR4 to mediate the Treg cell trafficking." (PMID 39184916, 2024). "In addition, we observed that the expression of CCL5, CD8A, and PD1 in the tumor tissue of mice in the combination therapy group was significantly higher than that in the control group, a result consistent with that of mIHC." (PMID 39183447, 2024).
tumor (continued). "Indeed, when the hydrogels were injected into mice tumor tissue, a sustained release of the nanoparticle complex was observed, which upregulated IRF5 expression and down-regulated CCL5 expression in tumors." (PMID 37587290, 2024). "In the present study, we found increased inflammation, lymphangiogenesis, M2-TAM, and CAFs in tumor tissues composed of cancer cells that originally promoted EMT induction, and CCL5 and IL-6 secreted by the inflammation further enhanced EMT induction in cancer cells." (PMID 39126553, 2024). "CCL5 and CCL18 upregulate various glycolysis-promoting factors, including hexokinase 2 (HK2), phosphoglycerate kinase 1 (PGK1), glucose-6-phosphate dehydrogenase (G6PD), and pyruvate kinase, further facilitating tumor progression." (PMID 38714539, 2024). "Additionally, under hypoxic and lactate-stimulated conditions, TAMs can secrete cytokines such as IL-6, CCL5, and CCL18 to promote glycolysis in tumor cells." (PMID 38714539, 2024). "Tumor cells promote the migration of myeloid-derived suppressor cells (MDSCs) and macrophages into the tumor microenvironment by secreting chemokines such as CCL2, CCL5, and CXCL12." (PMID 39717759, 2024). "Tumor cells infected with CCL5-modified OVs were able to produce CCL5 without compromising infectivity, thereby promoting NK cell accumulation and augmenting the therapeutic efficacy." (PMID 39055561, 2024). "Additionally, several immunosuppressive mediators, including CCL2, CCL5, CSF1, and TGFβ, secreted from CICs, are shown to promote macrophage and Treg recruitment into tumor tissue, while suppressing T cell responses, contributing to immune resistance." (PMID 38253555, 2024). "Currently, multiple studies seeking to potentiate anti-tumor responses, through CCR5 inhibition, are underway and may serve to better clarify the role of the CCL5/CCR5 axis in tumor control." (PMID 38928238, 2024). "Moreover, the expression of ADAM10 was reciprocally exclusive with some tumor immune checkpoint genes, such as VEGFB, LAG3, IL4, TNFRSF18, TNFRSF4, TNF receptor superfamily member 14 (TNFRSF14), CD27, CCL5, etc.." (PMID 39211038, 2024). "Interestingly, IDI1 represses CCL5- and CXCL10-expressing cells in the tumor microenvironment, increasing the capacity for immune evasion." (PMID 38927057, 2024). "Macrophages could be polarized to the tumor growth-promoting M2 subtype in the tumor environment by cytokines, such as CCL2, CCL5, CCL18, and TGFB1 and the mRNA levels of the transcription factor IRF4." (PMID 39272860, 2024). "Together, this suggests that the CCL5/CCR5 axis may have different, and possibly opposing, effects on the immune cell subsets mediating tumor growth and control." (PMID 38928238, 2024). "In conclusion, the study suggested that CCL4/CCL5 may interact with their receptors, CCR1/CCR5, facilitating the recruitment of γδ T cells to tumor regions." (PMID 38338658, 2024). "CCL5, CXCL9, CXCL10, CXCL11, and CX3CL1 are involved in the recruitment of CD8+ T cells to tumours." (PMID 38291183, 2024). "Results showed that depletion of CD73 only leads to the downregulation of CCL5 in tumor cells rather than other cell populations." (PMID 37291128, 2023). "In terms of its immunomodulatory function, the CCL5/CCR5 axis is known for creating a hospitable microenvironment for tumour cells by recruiting immunosuppressive cells, such as Tregs, MDSCs and TAMs to the tumour." (PMID 37170733, 2023). "CCL5 directly induce TAMs to secrete MMP9 and promote tumor cell metastasis." (PMID 37141250, 2023). "A pro-inflammatory environment induces the tumor secretion of plasminogen activator inhibitor-1 (PAI-1), stimulating the expression and secretion of chemokine CCL5 from endothelial cells, which acts in a paracrine fashion on TNBC cells to facilitate metastasis." (PMID 37887354, 2023). "Similarly, CCL5, which promotes CCR5-mediated CD8+ T cell infiltration to the primary tumor site, was upregulated in MOC2, SCC83, and CAL27, but not LY2 HNSCC cells." (PMID 37444444, 2023).
tumor (continued). "Additionally, in a different set of prostate cancer preclinical models, the pharmacologic inhibition of protein kinase D blunted the production of SCF, CCL5, and CCL11 and led to decreased MC migration and reduced tumor growth in vivo." (PMID 37376140, 2023). "While the hypoxic tumor microenvironment generates abnormal new blood vessels through both tumor-induced and CAF-induced factors, it also is a necessary factor for the conversion of NFs to CAFs, mediated through HIF1α-induced NFκB, CCL5, COL1A2, and αSMA." (PMID 37046676, 2023). "Overall, our results show that the switch of monocytes to the inflammatory subset and IFN-I signaling activation by PTBP2-overexpressing NB cells, which were responsible for the tumor-inhibiting effect, was independent of the CCL5/CCR5 axis." (PMID 37040518, 2023). "Additionally, autophagy inhibition enhances chemokine secretion (CCL5 and CXCL10) into the tumor bed." (PMID 38071322, 2023). "B cells can capture tumor antigens and activate immune cells in the initial stage of the immune response, or participate in tumor killing by secreting antibodies, such as CCL2, CXCR4, CCL5, CXCL5 and CXCL10, which trigger the activation of CD4 and CD8 T cells." (PMID 37254219, 2023). "Furthermore, Th17 cells were found to be responsible for CCL5 and CCL20 secretion, which are known to recruit CD8+ T cells (CCR5+ CCR6-) in the intraepithelial regions of the tumor." (PMID 37185750, 2023). "GBE1 knockdown can promote the secretion of CCL5 and CXCL10, and the recruitment of CD8+ T lymphocytes into the tumor microenvironment, suggesting that GBE1 may be an important target to inhibit the progression of LUAD tumor through immunotherapy." (PMID 37187527, 2023). "Given the importance of CCL5 and CXCL10 in mediating an anti-tumor immune response, these findings raise additional hypotheses regarding the significance of OSA cell intrinsic STING expression to effect radiation immunomodulation in vivo." (PMID 37079538, 2023). "Similarly, tumor cell-derived TGF-β signaling can trigger the release of several cytokines from CAFs, such as IL-6, CXCL10, and CCL5, which, in turn, drive the upregulation of glycogen metabolism in tumor cells through phosphoglucomutase 1 (PGM1) activation." (PMID 38002286, 2023). "As CCR5 binds with high affinity to several ligands that are induced by current BCa therapies (CCL5, CCL3 (MIP-1a), and CCL4 (MIP-1b), CCR5i may augment anti-tumor immune responses." (PMID 37759462, 2023). "The induction of CCL5 and CXCL10 chemokine expression induced by STING signaling appears particularly critical for recruiting immune effector cells such as CD8+ T lymphocytes and NK cells into the tumor microenvironment." (PMID 37079538, 2023). "In addition, CCL5 increased the number of fibroblasts in the TME, promoting tumor angiogenesis by enhancing VEGFA expression and fibroblasts transdifferentiation into vascular endothelial cells." (PMID 37141250, 2023). "Additionally, NK cell-derived chemokines including CCL5 and XCL1 can also mediated recruitment of DCs into the tumor leading to improved tumor control in murine solid tumor models." (PMID 38022679, 2023). "Dendritic cells (DCs) can recruit macrophages to the tumor via CCL2 and CCL5." (PMID 37371612, 2023). "These infiltrated immune cells and solid tumor cells release tumor-progressing cytokines (IL-6, TNF-α, TGF-β), chemokines (CCL2, CCL5, CCL18, CXCL8, CXCL12), and growth factors (EGF, PGF, IGF-1, IGF-2, PDGF) that promote tumor microenvironment immunosuppressive." (PMID 37371075, 2023). "While chronic inflammation promotes tumor progression, tumor cells themselves also attract immune cells via chemokines such as IL-8, CCL2 (MCP-1), CCL3 (MIP-1α), CCL5 (RANTES), CXCL6 (huGCP-2), and cytokines such as IL-1β, IL-6, TNFα, GM-CSF, and G-CSF, inducing inflammation." (PMID 36614196, 2023).
tumor (continued). "Secretion of VEGFC and CCL5 mediated by CRIP1 and CREB1 could reshape the tumor microenvironment into a suitable “soil” which could favor lymphangiogenesis and LM." (PMID 37409440, 2023). "T cells were found to be localizing selectively around a distinct malignant duct located center-left of the tissue section, with attributed genes such as immune checkpoint costimulatory receptor CD28, as well as IFIT3, CCL5, and PLAAT4 implicating an active anti-tumor immune response." (PMID 36906603, 2023). "In addition, the mRNA expression of IFNB1, CCL5 and CXCL10 was markedly increased in TRIM21-KO tumours after IR treatment." (PMID 36797289, 2023). "We further find that epigenetic priming induces increased tumor secretion of several key cytokines known to augment T and NK cell activation and cytotoxicity, including IL-6, IP-10 (CXCL10), KC (CXCL1), and RANTES (CCL5)." (PMID 37627156, 2023). "By modulating the expression or activity of CCL4 and CCL5, it may be possible to modulate the immune cell composition and activity within the TME, thereby impacting the tumor immune response." (PMID 38067251, 2023). "As for CCL5, strong or moderate staining in tumor tissue and negative staining in normal tissue were noticed." (PMID 37509334, 2023). "Furthermore, many other different molecules produced by tumor cells or by cells of the TME can induce MC chemotaxis, including CCL2, CCL5, CCL11, CCL15, CXCL12, VEGF, FGF2, osteopontin, and lipid mediators." (PMID 37376140, 2023). "In the current study, we found that tumor cell-autonomous CD73 facilitates Treg recruitment by transcriptionally upregulating CCL5 independent of its canonical effect." (PMID 37291128, 2023). "The reciprocal expression of CCL5 predominantly in ASCs and CCR1 largely in the tumor cells may indicate a specific chemokine receptor interaction in the 3D co-spheroids." (PMID 37444610, 2023). "Differential gene expression analysis indicated significant increases in inflammatory and effector gene expression, such as granzyme B (Gzmb) and CC-chemokine ligand 5 (Ccl5), in CD8+ T cells within the tumor microenvironment (TME) after PancVAX compared with isotype control–treated tumors (upper)." (PMID 38063199, 2023). "In addition, CCL5 and CCL9 chemokines led to the activation of MMPs, which induced remodeling of the ECM, promoting the migration of tumor cells from the primary site." (PMID 37686315, 2023). "Consistently, the production and expression of the chemokines CXCL1 and CXCL2, but not CCL3 and CCL5, were significantly upregulated in serum and tumor-infiltrating neutrophils from Arnt−/− mice." (PMID 36859266, 2023). "CCL5 expression was demonstrated to be dependent on direct cellular interaction and culture dimensionality of co-cultures of MDA-MB-231 tumor cells and adipose-tissue derived cells (ASCs or adipocytes), and was furthermore shown to be associated with specific up-regulation of the CCR1 receptor." (PMID 37444610, 2023). "Chemokines secreted by TAMs, including CCL3, CCL5, CCL15, CCL18, CXCL8 and CXCL12, promote tumor metastasis, angiogenesis, cancer cell survival, immunosuppression and resistance of cancer cells after chemotherapy via CCR1/5, CCR5, CCR1, CCR8, CXCR1/CXCR2, CXCR4, respectively." (PMID 36173487, 2023). "Furthermore, MEPs increased the tumor cell killing activity of CD8 + T cells and NK cells, an effect that was dependent on MEP-secreted CCL5 and CXCL16." (PMID 36646904, 2023). "Chemo-attractants/receptors (including CCL5/CCR5, CCL27/CCR10 and CX3CL1/CX3CR1) and immunomodulation of chemokine axes (including HLA-G and CD47) are involved in controlling NK cell recruitment to the tumor." (PMID 37064113, 2023). "Due to the tumor-promoted mechanisms of HOXC11 remains unclear, we used GSEA to enrich some HOXC11 expression-related genes, including CCL5, HBA2, and SPHK1, and then detected their mRNA expressive levels in HOXC11 overexpressed cells." (PMID 36823149, 2023).
tumor (continued). "Indeed, the co-expression of Oct4/Sox2 inhibits the expression of the C-C Motif Chemokine ligand 5 (CCL5) and C-X-C Motif Chemokine ligand 9, 10 and 11 (CXCL 9,10 and 11), which mediate CD8+ T cell attraction against tumor cells." (PMID 36831383, 2023). "If these receptors on tumor cells are similarly inhibited by RANKL, then inhibition of RANKL by denosumab would increase their expression and enhance pro-tumoral signaling by the osteoid cell-derived chemokines CCL2, CCL5, CXCL16, and CX3CL1." (PMID 37025604, 2023). "On one hand, these microparticles recruit monocytes producing IFN-γ and IL-4, which are involved in the tumoricidal function of macrophages, via the chemoattractants RANTES/CCL5, MIF (macrophage migration inhibitory factor), CCL2 and CXCL12; thus, they suppress primary tumor growth." (PMID 36831450, 2023). "Moreover, tumor growth inhibition was inversely correlated with levels of CCL4, CCL5, and MDSCs after treatment with EVT801, either alone or combined with ICT." (PMID 36970050, 2022). "As already mentioned, TAMs are a heterogeneous population that includes resident cells of embryonic origin present at birth and invading monocytes/macrophages recruited during early carcinogenesis by chemokines secreted by tumor and stromal cells (such as CCL2, CCL5, and CSF-1)." (PMID 35183252, 2022). "It induces high amounts of CCL5 and CXCL10 in tumor cells with distinct kinetics." (PMID 36429101, 2022). "Besides, MDSCs can produce high levels of some chemokines, such as CCL3, CCL4, and CCL5, which drive CCR5-expressing Treg cells through the tumor microenvironment, supporting the tumor growth." (PMID 35757002, 2022). "TAM recruitment is mainly mediated by tumor cells and surrounding stromal cells through the release of diverse chemokines, including CCL5 and CCL2, and stromal glycoproteins can promote tumor progression by facilitating TAM recruitment from the circulation and/or local tissue to the tumor site." (PMID 35327584, 2022). "Although the role of CCL5/CCR5 axis in carcinogenesis is controversial, increasing evidence has demonstrated that constitutive CCL5 expression enables tumor immune recognition and enhances immunotherapy response via increased infiltration of CD8+ T cells into tumors." (PMID 36352411, 2022). "Furthermore, NK cells in tumour tissues produce chemokines, such as CXCL1, CCL5, and FMS-like tyrosine kinase 3 ligands, which affect cDC1." (PMID 36298556, 2022). "Tumor cells also recruit platelets into the tumor microenvironment (TME), and platelets are activated by tumor cells to release the cytokines VEGF, CCL5, PDGF, TGFβ, PG, TPM3, LPA, PF4, PAF, and HGF, which promote the epithelial-mesenchymal transition of tumor cells." (PMID 35836573, 2022). "At the invasive front of CRC, tumor bud-derived CCL5 can recruit fibroblasts via CCR5-SLC25A24 signaling, further promoting angiogenesis and collagen synthesis via recruited fibroblasts, and eventually create a tumor-promoting microenvironment." (PMID 35241150, 2022). "Without accessory transgenes (CCL5 and IL-15), high doses of unarmed oncolytic-adenovirus controlled tumour growth without the need for CAR T cells, but synergised with CAR T cells at lower doses, with modest effects on CAR T cell persistence noted." (PMID 35205725, 2022). "CCL5 also recruits fibroblasts via the SLC25A24-pAkt-pmTOR signaling pathway in fibroblasts, which further promotes angiogenesis and collagen synthesis through recruited fibroblasts, ultimately creating a pro-tumor microenvironment." (PMID 36387070, 2022). "(ii) Antitumor immune-related molecules including CXCL10, CXCL9, CXCR3, CCL5, and CCL4 belong to the chemokine family and have been reported in several studies to recruit immune cells such as cytotoxic T lymphocytes (CTL) and NK cells to kill tumor cells." (PMID 35479936, 2022).